SIRT2 (sirtuin 2)
Diseases named in the same sentence as SIRT2 in open-access papers (continued):
Sharing a sentence is not in itself a finding about the gene and the disease.
leukemia (17 papers, 2013 to 2022). A malignant (clonal) hematologic disorder, involving hematopoietic stem cells and characterized by the presence of primitive or atypical myeloid or lymphoid cells in the bone marrow and the blood. "Considering this background, our study was designed to investigate the anti-proliferative effect of BJe in human leukemia monocytic THP-1 cells, focusing on the potential involvement of SIRT2 underlying the mechanism of action." (PMID 36297603, 2022). "The effect of MC2494 derivatives on SIRT1 and SIRT2 protein expression was then investigated in leukemia U937 cells by Western blot." (PMID 31726691, 2019). "NAD-dependent deacetylase Sirtuin 2, encoded by the SIRT2 gene, promotes NADPH production and leukemia cell growth through deacetylating G6PD." (PMID 31500396, 2019). "Here, SIRT2 protein expression in leukemic cell lines indicated that SIRT2 is a target for treatment of leukemia." (PMID 30081901, 2018). "The anti-proliferative effect of SIRT2 inhibitors merits further explorations in leukaemia mouse models and clinical trials." (PMID 27586085, 2016). "We next explored the functional role of acetylation regulation of G6PD by SIRT2 in leukaemia cell proliferation." (PMID 27586085, 2016). "The expression of SIRT2 was much higher in the primary leukemia cells from ALL patients and in ALL cell lines than normal cells." (PMID 25884180, 2015). "Activation of G6PD by SIRT2 supports the proliferation and clone formation of leukaemia cell." (PMID 33630390, 2021). "In leukaemia cells, SIRT2 promotes cell proliferation via enhancing the production of NADPH25." (PMID 30584257, 2018). "Activation of G6PD by SIRT2 supports the proliferation and clonogenic activity of leukaemia cells." (PMID 27586085, 2016). "The observation that SIRT2-induced activation of G6PD contributes to leukaemia indicates that inhibiting SIRT2 with small molecule inhibitors may serve as a substitutive strategy to suppress G6PD." (PMID 27586085, 2016). "Therefore, SIRT2 likely modulates the downstream components of the RAR-α pathway to induce granulocytic differentiation in leukemia cells." (PMID 23460888, 2013). "In addition, activation of G6PD by SIRT2 supports the proliferation of leukaemia cell." (PMID 33630390, 2021). "Moreover, SIRT2 can induce the cell proliferation of leukaemia and resistance to apoptosis." (PMID 31727006, 2019). "Chemical inhibitors against SIRT2 suppress G6PD activity, leading to the reduced cell proliferation of leukemia cells." (PMID 35207558, 2022). "To this end, we examined the physiological significance of the interaction between SIRT2 and G6PD in leukaemia cells." (PMID 27586085, 2016). "Taken together, our study reveals that deacetylation of G6PD by SIRT2 sustains NADPH production and promotes leukaemia cell proliferation." (PMID 27586085, 2016). "Chemical inhibitors against SIRT2 effectively impaired G6PD activity and suppressed the proliferation of leukaemia cells." (PMID 27586085, 2016). "The general results of leukemia have shown that: (i) SIRT2 and SIRT3 can be considered as important prognostic markers for the disease, (ii) in ALL, SIRT2 participates in processes such as tumor growth and (iii) in CLL, SIRT3 acts in the control of reactive oxygen species." (PMID 36230534, 2022). "Additionally, we screened their effect on the enzymatic activity of the histone deacetylase sirtuin family (SIRT1, SIRT2, SIRT3, SIRT5 and SIRT6) using both recombinant enzymes and nuclear lysates from leukemia cells." (PMID 32587297, 2020). "Firstly, by treating leukemia U937 cells with the analogs and comparing their biological activity to that induced by MC2494, we detected a decrease in the expression level of SIRT1 and SIRT2." (PMID 31726691, 2019).
leukemia (continued). "SIRT2-specific inhibitors effectively suppressed the proliferation of leukaemia cells, but not normal hematopoietic cells." (PMID 27586085, 2016). "To test the preference of SIRT2 inhibitors, we isolated normal hematopoietic stem and progenitor cells (HSPCs) and found that SIRT2-specific inhibitors (AGK2 and SirReal2) selectively decreased the proliferation of mouse leukaemia cell RAW264.7, but not HSPCs." (PMID 27586085, 2016). "Chemical inhibitors against SIRT2 suppress G6PD activity, leading to reduced cell proliferation of leukaemia cells, but not normal hematopoietic stem and progenitor cells." (PMID 27586085, 2016). "However, we found that shRNAs or chemical inhibitors against SIRT2 downregulated G6PD activity and suppressed leukaemia cell growth irrespective of Myc expression level." (PMID 27586085, 2016).
non-small cell lung carcinoma (17 papers, 2015 to 2025). A group of at least three distinct histological types of lung cancer, including non-small cell squamous cell carcinoma, adenocarcinoma, and large cell carcinoma. "Previous studies also showed that SIRT2 was significantly downregulated in non-small cell lung cancer." (PMID 31932479, 2020). "SIRT2 negatively regulates JMJD2A expression in human non-small cell lung cancer tissues." (PMID 30574122, 2018). "SIRT2 suppresses non-small cell lung cancer growth by targeting JMJD2A." (PMID 28514749, 2017). "SIRT2 inhibits non-small cell lung cancer cell growth through impairing Skp2-mediated p27." (PMID 28514749, 2017). "The precise role of SIRT2 in tumors is still a matter of debate with some reports showing a correlation between SIRT2 levels and poor prognosis in non-small-cells lung cancer or progression of cervical cancer, whereas others report a correlation between low levels of SIRT2 and non-small lung cancer." (PMID 26798421, 2016). "In addition, SIRT2 induces Skp2 deacetylation and subsequent degradation, then promoting p27 protein level in non-small cell lung cancer." (PMID 27794562, 2016). "Interestingly, other members of the sirtuin family are linked to ROS generation; sirtuin 2 overexpression induced ROS generation in non-small-cell lung cancer, and sirtuin 2 was reported to induce alveolar mitochondrial biogenesis in the animal model of Staphylococcus aureus pneumonia." (PMID 25839054, 2015). "A recent experiment has shown that sirtuin 2 (SIRT2) increases the mRNA stability of transcription factor EB (TFEB) and induces the release of exosomes to trigger autophagy and decrease apoptosis in non-small cell lung cancer cells." (PMID 35765040, 2022). "Moreover, compound 8 is a potent SIRT2 inhibitor and can effectively inhibit the growth, invasion and migration of non-small cell lung cancer (NSCLC) cells, providing more references and options for the research of SIRT2 targeted cancer treatment." (PMID 35521274, 2020).
Hepatic steatosis (16 papers, 2021 to 2025). Steatosis is a term used to denote lipid accumulation within hepatocytes. "Together, these results suggest that the loss of SIRT2 promotes hepatic steatosis, a hallmark of NAFLD, independently of diet." (PMID 35743232, 2022). "We next sought to determine the mechanisms underlying increased hepatic steatosis in SIRT2-KO mice fed a HFD." (PMID 35743232, 2022). "Liver-specific SIRT2 deficiency sensitized mice to ALD, whereas transgenic SIRT2 overexpression in hepatocytes significantly prevented ethanol-induced liver injury via normalization of hepatic steatosis, lipid peroxidation, and hepatocyte apoptosis." (PMID 34642310, 2021). "Therefore, the present study aimed to determine the effects of SIRT2 on the regulation of hepatic steatosis in cells and in mice and to explore the underlying signaling pathways." (PMID 35743232, 2022). "Targeting the SIRT2–HNF4α axis holds promise for treating fatty liver diseases and metabolic disorders in obese individuals." (PMID 40076884, 2025). "SIRT2 has been shown to prevent hepatic steatosis and metabolic disorders through the deacetylation of HNF4α, and the upregulation of HNF4α acetylation levels increases hepatic lipid accumulation." (PMID 37239836, 2023). "Restoration of hepatic SIRT2 expression in HFD-fed mice largely alleviated hepatic steatosis, whereas SIRT2 liver-specific ablation exacerbated these metabolic dysfunctions." (PMID 38136219, 2023). "To determine the role of SIRT2 in HFCS-induced hepatic steatosis, we successfully obtained SIRT2 KO mice based on Clustered Regularly Interspaced Short Palindromic Repeats (CRISPR)/CRISPR-associated protein 9 (Cas9) system." (PMID 37240315, 2023). "In summary, our data demonstrate that PGC-1α ameliorates hepatic steatosis and hinders progression to steatohepatitis, possibly via the SIRT2-PGC-1α-NAD+ feedback loop." (PMID 39871927, 2022). "The dysregulation of some metabolic genes involved in lipogenesis and FAO in SIRT2-KO together with the increased hepatic lipid accumulation suggest that SIRT2 has a crucial role in regulating hepatic steatosis." (PMID 35743232, 2022). "In the context of hepatic metabolism, Sirt2 emerges as a protector against fatty liver disease and hepatic steatosis by stabilizing HNF4α via deacetylation, thus promoting the expression of genes involved in lipid, amino acid, and glucose metabolism, and influencing inflammatory networks." (PMID 39334926, 2024). "Moreover, histology analysis showed a more severe presence of hepatic steatosis and higher lipid storage in the liver of SIRT2 KO mice, characterized by increased lipid droplets." (PMID 37240315, 2023). "To determine whether SIRT2 has a role in hepatic steatosis, we performed hematoxylin and eosin (H&E) staining of liver sections that revealed normal structural features of hepatocytes from WT and SIRT2-KO mice fed a CD." (PMID 35743232, 2022). "Interestingly, SIRT2-KO mice fed a CD spontaneously exhibit increased hepatic steatosis when compared to WT mice." (PMID 35743232, 2022). "Furthermore, it has been recently demonstrated that SIRT2 prevents liver steatosis by deacetylating the transcription factor hepatocyte nuclear factor 4α (HNF4α)." (PMID 35743232, 2022). "Moreover, SIRT2 ablation leads to hepatic steatosis independently of diet and increased ER stress response." (PMID 35743232, 2022). "Importantly, SIRT2-KO mice exhibited worsened hepatic steatosis independently from diet, consistent with upregulated gene expression of lipogenic enzymes and increased expression of ER stress markers." (PMID 35743232, 2022). "Overexpression of SIRT2 reduces the stability of the ACLY protein, inhibits lipid accumulation in hepatocytes, and reduces hepatic steatosis in mice fed with HFD." (PMID 36008973, 2022). "SIRT2, SIRT3, and SIRT4 upregulation induced by an investigational molecule also prevented the progression of hepatic steatosis and fibrosis in obese rats." (PMID 35203484, 2022).
Hepatic steatosis (continued). "The sirtuin 2 (SIRT2) protein deacetylase is emerging as a new player in metabolic homeostasis, but its role in the development of hepatic steatosis and its link with ER stress activation remains unknown." (PMID 35743232, 2022). "However, the putative role of SIRT2 in the regulation of hepatic steatosis and the interplay with ER stress has not been previously investigated." (PMID 35743232, 2022).
colon cancer (14 papers, 2017 to 2025). "Loss of SIRT2 leads the endogenous FOXO1 acetylated in colon cancer by dissociating from SIRT2 and binding acetylated FOXO1 to the E1-like protein Atg7, which affects the autophagy process that leads to cell death and thus exerts an oncogenic effect." (PMID 39479446, 2024). "In addition, the overexpression of SIRT2 was significantly associated with an increase of AKT phosphorylation in PADI3-expressing HCT116 colon cancer cells." (PMID 36297603, 2022). "Interestingly, decreased SIRT2 expression was associated with adverse clinicopathological features and poor prognosis in colon cancer." (PMID 33014852, 2020). "In the future, in patients with hypoacetylated colon cancer, the efficacy of reversing K153 acetylation level, probably by inhibiting SIRT2, can be tested as an adjuvant therapy for CRC." (PMID 36812247, 2023). "For example, Ozden O. and Parkin S-H demonstrated that SIRT2 affects the expression of oncogenic FOXM1 in HCT116 colon cancer cells leading to a decrease in the number of colony formations and proliferation." (PMID 35326523, 2022). "Inhibition of SIRT2 expression also confers resistance to targeted therapies in KRAS-mutant colon cancers." (PMID 28514749, 2017). "Moreover, colon cancer progression is influenced by the SIRT2 through its regulation of NF-κB and CSN2, triggering the NF-κB/CSN2 signaling axis that induces Snail expression and enhances metastatic potential." (PMID 41428704, 2025). "Moreover, overexpression of SIRT2 induces cell cycle S phase arrest of normal cells and colon cancer cells." (PMID 35326523, 2022). "Treatment of HCT116 cells with AF8 or AF10 potently inhibited colony formation and significantly reduced tumor growth in a colon cancer xenograft mouse model, suggesting that thiocarbamoyl pseudopeptides may exhibit therapeutic potential for Sirt2 inhibition in cancer." (PMID 38474697, 2024). "PADI3 promotes cell cycle arrest via Sirt2-AKT-p21 and functions as a tumor suppressor gene in colon cancer." (PMID 36358967, 2022). "Sirtuin 2 (SIRT2) mediates the deacetylation of isocitrate dehydrogenase (NADP (+)) 1 (IDH1), thereby, promoting IDH1 activity and the production of α-ketoglutarate (α-KG), inhibiting liver metastasis of colon cancer and improving prognosis." (PMID 35004688, 2021). "Meanwhile, in a separate study SIRT2 was found to be downregulated in colon cancer biopsies compared to adjacent noncancerous tissues, and overexpression of SIRT2 inhibited the proliferation and metastatic progression of SW480 cells." (PMID 34899841, 2021).
depression (14 papers, 2015 to 2025). "There is a growing body of evidence that SIRT1 and SIRT2 may have a role in depression, linked to inflammation." (PMID 33669121, 2021). "Thus, in this short article, we review the association of SIRT1 and SIRT2 activity and depression, and evidence of the effects of SIRT1 and SIRT2 modulators on inflammation in vitro and depressive-like behaviours in vivo." (PMID 33669121, 2021). "Furthermore, polymorphisms or genetic variation in SIRT1 and SIRT2 in the normal and depression populations have also been studied to investigate the genetic association of SIRT1 and SIRT2 and the susceptibility, onset and course of depression." (PMID 33669121, 2021). "To investigate whether hippocampal SIRT2 is implicated in depression-related behaviors, we constructed an overexpression SIRT2 vector." (PMID 25672834, 2015). "Regarding its role in neurogenic processes, SIRT2 has been implicated in the differentiation of dopaminergic neurons in the substantia nigra of mice, and recent work has revealed a link between decreased levels of SIRT2 in animal models of depression and reduced hippocampal neurogenesis." (PMID 41154588, 2025). "Combined, studies surmise that SIRT2 inhibition improves depression-like behaviors via glutamatergic and serotonergic signaling changes." (PMID 39404407, 2024). "There is evidence to support a proactive role for SIRT2 inhibition in depression across multiple domains and animal models, including a model of depression with reduced olfactory sensation." (PMID 39404407, 2024). "Two important members, SIRT1 and SIRT2, have been found to participate in the pathophysiology of depression." (PMID 33669121, 2021). "This review will discuss the evidence to date in relation to the purported role of SIRT1 and SIRT2 modulators in the treatment of depression." (PMID 33669121, 2021). "In the VGLUT1+/- model of depression, Sirt2 was elevated, and its inhibitor 33i acted as an antidepressant in the sucrose preference test." (PMID 35011254, 2021). "To explore the effect of SIRT2 inhibition on depression-related behaviors, we treated rats with tenovin-D3 for 14 days." (PMID 25672834, 2015). "In this study, we examined the effects of SIRT2 on hippocampal neurogenesis and behaviors in a chronic unpredictable stress model of depression and the involvement of hippocampal neurogenesis in the antidepressant-like behavioral effects of SIRT2." (PMID 25672834, 2015). "However, it is important to acknowledge the need for further exploration of how S‐KET modulates depression‐related neural circuits, particularly its interaction with SIRT2 and the roles of microglia and neurons in this process in future studies." (PMID 40171943, 2025). "It is thought that SIRT2 may collaborate with SIRT1 in the pro-inflammatory cascade in depression, and inhibition of SIRT2 may aid in ameliorating downstream changes in MDD." (PMID 39404407, 2024). "However, in the CUS model of depression, Sirt2 expression in the Hp decreased and was reversed by fluoxetine treatment." (PMID 35011254, 2021). "Although it is possible that other SIRTs, such as SIRT1 and SIRT2, might also regulate neurogenesis, aging, and even depression, we decided to focus only on SIRT3 in this study, given its central role in mitochondrial metabolism and oxidative protection." (PMID 35011652, 2021). "Therefore, in order to fully understand the role of SIRT1 and SIRT2 modulators, and potential treatment guidelines in the clinical setting, there needs to be consideration of the impact of sex in animal models of depression." (PMID 33669121, 2021). "This opposite role of Sirt1 and Sirt2 is thought to be age-dependent, and the balance of these two Sirts might be crucial in part for the regulation of depression by Sirt1." (PMID 29643977, 2018). "It has been reported that Sirt1 is mostly believed to be neuroprotective while Sirt2 may enhance or facilitate neurodegeneration in stress-related psychiatric disorders including depression." (PMID 29643977, 2018).